REPS2 (RALBP1 associated Eps domain containing 2)
Description:
Involved in ligand-dependent receptor mediated endocytosis of the EGF and insulin receptors as part of the Ral signaling pathway. By controlling growth factor receptors endocytosis may regulate cell survival. Through ASAP1 may regulate cell adhesion and migration.
Synonyms: POB1
Tractability: Antibody: its Gene Ontology location is reachable by antibodies, with medium confidence. PROTAC: its protein half-life has been measured.
Gene: Protein-coding gene on chromosome X (16,946,658 to 17,153,272, forward strand). Ensembl gene ENSG00000169891.
Subcellular location: Cytoplasm
Pathways (Reactome):
Vesicle-mediated transport: Cargo recognition for clathrin-mediated endocytosis; Clathrin-mediated endocytosis
Gene Ontology:
Molecular function: protein binding; calcium ion binding; protein-macromolecule adaptor activity
Biological process: epidermal growth factor receptor signaling pathway; protein-containing complex assembly
Cellular component: cytoplasm; cytosol
Homologues: Orthologues: chimpanzee REPS2 (99% identical), macaque REPS2 (98% identical), pig REPS2 (91% identical), dog REPS2 (90% identical), mouse Reps2 (87% identical), rat Reps2 (86% identical), rabbit REPS2 (79% identical), guinea pig REPS2 (78% identical), tropical clawed frog reps2 (53% identical), zebrafish reps2 (26% identical). Paralogues in human: REPS1 (41% identical), EPS15L1 (20% identical), EPS15 (19% identical), ITSN2 (18% identical), ITSN1 (18% identical), EHD1 (8% identical), EHD3 (8% identical), EHD4 (8% identical), EHD2 (8% identical), SRL (5% identical).
Diseases named in the same sentence as REPS2 in open-access papers:
REPS2 is named in the same sentence as 12 diseases in open-access papers, as found by Europe PMC text mining. Sharing a sentence is not in itself a finding about the gene and the disease. The quoted sentences say what the papers report.
esophageal squamous cell carcinoma (3 papers, 2016 to 2023). Esophageal squamous cell carcinoma (ESCC) is a type of esophageal carcinoma (EC) that can affect any part of the esophagus, but is usually located in the upper or middle third. "Previous studies on RALBP1 associated Eps domain containing 2 (REPS2, also known as POB1) mostly focus on cancer, such as breast cancer, esophageal squamous cell carcinoma and prostate cancer." (PMID 36600215, 2023).
breast carcinoma (2 papers, 2020 to 2023). "The expression of Meis1, along with transmembrane protein 25 (Tmem25) and Reps2, has been suggested to be a marker for breast cancer prognosis." (PMID 33402862, 2020). "High expression of Meis1, Tmem25, and Reps2 is a determining factor for evaluating the probability of relapse and survival of breast cancer." (PMID 33402862, 2020).
prostate carcinoma (2 papers, 2012 to 2016). A carcinoma that arises from epithelial cells of the prostate gland. "REPS2 is found to be involved in EGF signaling pathway in prostate cancer." (PMID 27120794, 2016). "The expression of this gene might serve as a biomarker of favorable outcome in breast and prostate cancers; conversely, REPS2 downregulation has been demonstrated in the progression of prostate cancer." (PMID 22976541, 2012).
colon tumors (1 paper, 2015). "Thus, ALDH1A1 and REPS2 (mutated in 14/700, (2%) of colon tumors, and in 4/700, (0.57%) of colon tumors, respectively; Cosmic database) seem to be major mediators of nuclear DKK-1 effects." (PMID 25788273, 2015).
tumor (7 papers, 2012 to 2024). "Since both BASP1 and REPS2 have been shown to possess tumor-suppressive activities, it will be worthy of further investigation to decipher their potential signaling network with ELAVL2." (PMID 38548861, 2024). "The additional nucleotides corresponded to 136 bp of complete exon 6 of RALBP1 associated Eps domain containing 2 (REPS2) (NM_004726.2) and 50 bp of complete exon 5 of SSX1, indicating a complex rearrangement in this tumor." (PMID 22976541, 2012). "These researches suggest that signals from REPS2 might suppress tumor growth and metastasis through RalBP1/RAC1/CDC42 signaling pathway." (PMID 27120794, 2016). "Furthermore, we have provided the following series of evidence that miR-675-5p induced ESCC cell G1-S transition and promoted tumor growth, proliferation, migration, tumor metastasis and tumorigenicity in part by suppressing REPS2." (PMID 27120794, 2016). "At later stages in human tumors, systemic therapy can cause the selection of tumor cells with high nuclear DKK-1 that by inducing genes such as ALDH1A1 and REPS2 may be responsible for chemoresistance." (PMID 25788273, 2015). "Among the upregulated genes, MBNL2, SEPT4, REPS2, OTUD5, and TXNIP were shown to play a tumor-suppressive role in many tumors." (PMID 36428626, 2022). "Consist with the previous researches, our data demonstrated that inhibition of REPS2 would activate RalBP1/RAC1/CDC42, increase MMP2/9, thus promote tumor invasion and metastasis." (PMID 27120794, 2016). "Next, 200 cells from the high and low gate were sorted for qPCR analysis for a subset of tumor markers such as AMACR, CAMKK2, TMEFF2, REPS2 and ABCC4." (PMID 25514598, 2015). "In line with our previous observations, the tumor markers AMACR, CAMKK2, TMEFF2, REPS2 and ABCC4 were significantly expressed in AMACR high cells as compared to AMACR low cells." (PMID 25514598, 2015). "In order to disclose the molecular mechanism through which miR-675-5p realizes its tumor-stimulative functions, computational prediction using open access websites including miRDB, DIANA-MICROT, MICRORNA.ORG and TargetScan found that REPS2 was a strong potential target." (PMID 27120794, 2016).
cancer (3 papers, 2015 to 2016). A tumor composed of atypical neoplastic, often pleomorphic cells that invade other tissues. "What is more, REPS2 plays important roles in inhibiting cell proliferation and migration of cancer cells." (PMID 27120794, 2016). "In addition, emerging evidences have shown that REPS2 plays important roles in inhibiting cell proliferation, migration of cancer cells." (PMID 27120794, 2016). "Moreover, we show that DKK-1 regulates several cancer-related genes including the cancer stem cell marker aldehyde dehydrogenase 1A1 (ALDH1A1) and Ral-binding protein 1-associated Eps domain-containing 2 (REPS2), which are involved in detoxification of chemotherapeutic agents." (PMID 25788273, 2015).
immune disease (1 paper, 2022). "No direct effect of REPS2 on auto-immune disease has been recognized to date." (PMID 35721087, 2022).
neurodegenerative disease (1 paper, 2023). A disorder of the central nervous system characterized by gradual and progressive loss of neural tissue and neurologic function. "However, we still do not know the roles of many key drivers identified in this study in the development of neurodegenerative diseases, such as REPS2 and FXYD1." (PMID 37284017, 2023).
REPS2 also shares sentences with these, for which no sentence is quoted: colorectal cancer (1 paper); cryptorchidism (1); esophageal cancer (1); synovial sarcoma (1).